IL6 (interleukin 6)
Diseases named in the same sentence as IL6 in open-access papers (continued):
Sharing a sentence is not in itself a finding about the gene and the disease.
depression (continued). "Another study suggested PROVIT (probiotics and vitamins) as an efficient adjunct therapy that could decrease inflammation and manage symptoms based on reductions in depression scores and IL-6 gene expression levels." (PMID 37448433, 2023). "For example, chronic depression and elevated depression severity at follow-up could be predicted by higher IL-6 levels." (PMID 36966195, 2023). "Higher levels of IL-6 correlated with poorer PaO2 levels, and with greater severity of depression." (PMID 37623458, 2023). "Together, these findings suggest that increased IL-6, TNF-α and neopterin may be associated with increased depression, including in people living with HIV." (PMID 37693812, 2023). "In addition, mendelian randomization analyses suggested that IL-6, CRP are likely to be causally linked with depression." (PMID 37344456, 2023). "In addition, depression induced by IL-6 can result in a reduction in food intake, an increase in resting energy expenditure, and a suppression of anabolic hormones such as growth hormone and insulin-like growth factor (IGF)-1." (PMID 37763079, 2023). "No singlecare-related variable and only one biomarker (IL-6) were associated with depressionin the univariate analysis.Interestingly, only IL-6 levels were independently associated with depression in oursample." (PMID 37712803, 2023). "Second, while minocycline might weaken a depression symptom network, the finding that IL-6 remained connected to the network indicates that minocycline might not supress all immune activation." (PMID 37723153, 2023). "Much-blooming evidence states that systemic inflammation may result in depression, and IL-6 mainly plays an essential role in human and animal models of depression." (PMID 38155869, 2023). "Another double-blind randomized controlled trial also demonstrated that significant improvement in depression and anxiety symptoms as well as attenuation of cytokine IL-1α and IL-6 were observed in subjects on probiotics (daily intake for 30 days) compared with controls on placebo." (PMID 38051740, 2023). "Particularly, levels of interleukin-1 and interleukin-6 are also increased in depression." (PMID 38138286, 2023). "Additionally, given the amygdala’s regulatory role in IL-6 secretion, we examine the pathways from the amygdala to IL-6 secretion and depression under gene-stressor interactions." (PMID 37324818, 2023). "Similarly, depression is associated with elevated C-Reactive Protein (CRP) and Interleukin-6 (IL-6) levels, while anxiety is associated with an increase in CRP, TNF-α, and Interferon-γ (IFN-γ) levels." (PMID 37251220, 2023). "Indeed, IL-6 and CRP levels are associated with depression severity, predict cognitive impairments in depression, and are further aggravated by acute stress." (PMID 37764744, 2023). "Notably, the baseline level of IL-6 seems promising in predicting an antidepressant treatment outcome in children and adolescent depression." (PMID 34590201, 2023). "IL-6, CRP, and triglycerides (TG) may be causally related to depression and therefore may be targets for treatment and prevention of mental sickness." (PMID 38084332, 2023). "A recent Mendelian Randomisation (MR) study suggested that CRP may decrease and IL-6 may increase anxiety and depression symptoms." (PMID 37217205, 2023). "In particular, depression might lead to reduced TGF-β plasma levels and subsequently induce inflammation through increased serum levels of IL-8, associated with decreased IL-6 and TGF-β levels." (PMID 38138916, 2023). "We showed that blunting of the IL-6 diurnal pattern was associated with both amygdala (especially BLA) hypoactivity in response to fearful (vs. neutral) faces and greater depressive symptoms in a sizeable community sample with various levels of depression." (PMID 37324818, 2023).
depression (continued). "In the present study, we found that maternal separation led to anxiety- and depression-like behaviors in offspring, the upregulation of the hippocampal levels of pro-inflammatory cytokines (IL-1β, IL-6, and TNF-α), and the inhibition of the Sirt1/NF-κB signaling pathway." (PMID 37273278, 2023). "Interestingly, while protein levels of IL-6 in plasma showed a tendency for increase, its mRNA levels in PBMCs were significantly downregulated (p < 0.001) in depression patients compared with healthy controls." (PMID 37575572, 2023). "In addition, the investigation of depression subgroups showed that comparing individuals with normal depression scores with the group with high scores resulted in significantly higher values of IL-6 and FBG and significantly lower values of IL-." (PMID 38068839, 2023). "In the case of IL-6, literature has been supporting an increase in plasma of depression patients." (PMID 37575572, 2023). "Increased levels of pro-inflammatory cytokines IL-6, IL-8, and IL-18 in nurses with moderately-severe depressive symptoms support a meta-analysis of inflammatory markers in depression studies that identify depression as a pro-inflammatory state." (PMID 37637801, 2023). "Paroxetine directly affects the macrophage response to inflammatory stimuli, for example, paroxetine significantly inhibits LPS-induced IL-6 production, which may be one of the mechanisms of action for its therapeutic effect on depression." (PMID 37275977, 2023). "One of such studies demonstrated increased IL-6 levels in women with depression during late pregnancy and early postpartum period, whereas another study showed a decreased interferon-gamma/IL-10 ratio, which may indicate impaired cell-mediated immunity." (PMID 37840785, 2023). "IL-6 is a peripheral or central cytokine that plays a significant role in stress responses and depressive disorders, particularly physical illnesses that coexist with depression, according to evidence from animal and human studies." (PMID 37745719, 2023). "TNF-α and IL-6 induce the production of indoleamine 2,3 -dioxygenase (IDO), leading to a decrease in tryptophan and the production of tryptophan metabolites, which are associated with depression." (PMID 36860860, 2023). "Considering the relationship between estrogen, inflammation, and depression, we hypothesized that estradiol can regulate the IL-6/sIL-6R/sgp130 signaling pathway and improve MDD." (PMID 37828513, 2023). "IL-6 was significantly elevated and highly correlated with major depressive disorder." (PMID 36120298, 2022). "Moreover, in people suffering from depression, previous studies have shown an increase in proinflammatory cytokines such as TNFα and IL-6, similar to that in psoriasis." (PMID 35163689, 2022). "The expression levels of pro-inflammatory cytokines, such as tumor necrosis factor alpha (TNF-α), interleukin (IL)-6 and IL-1β have been found to be elevated in the peripheral blood or central nervous system (CNS) of patients suffering from major depressive disorder (MDD)." (PMID 36558541, 2022). "Indeed, in a cumulative meta-analysis in adult patients with clinical depression, conducted on 58 observational studies, it was concluded that IL-6, CRP, and TNF-α were more strongly associated with severe depression than with moderate depression." (PMID 35360574, 2022). "Controlling symptoms such as pain and fatigue by inhibiting IL-6 may prove promising for decreasing depression levels in patients with RA." (PMID 36422176, 2022). "However, a recent study that investigated the effect of anti-IL6 treatment with tocilizumab on depression in the critically ill found significantly higher depression scores 28 days post-drug administration." (PMID 34648616, 2022).
depression (continued). "In the smoking-CRP, smoking-IL-6 activity, smoking-depression, and depression-smoking analyses, all of the global estimates calculated using robust MR methods, excluding the MR-Egger estimate, showed a similar increase in the odds of the outcome and higher levels of the exposure." (PMID 36057695, 2022). "The IL-6 pathway is therefore a hypothetical mechanism linking smoking behavior with depression." (PMID 36057695, 2022). "As expected, IL-6 was a predictor of depression symptoms in our univariate regression model, although, to our surprise, urinary IL-6 had an inverse correlation with level of depression symptoms." (PMID 36299996, 2022). "In fact, psoriasis and depression are reported to share biological mechanisms such as the high levels of proinflammatory cytokines interleukin (IL)-1 and IL-6, thus showing that an inflammatory process might be involved in both diseases progressing." (PMID 35206248, 2022). "Depression is also found to have an association with IL-6, regardless of other factors of depression that occurred during the COVID-19 pandemic." (PMID 36040960, 2022). "Higher levels of TNF-α and IL-6 have been found in the blood of patients with depression." (PMID 35573384, 2022). "However, our results were consistent with previous research showing that IL-6 more consistently predicts stress levels and depression than CRP." (PMID 35873737, 2022). "The IL-6 pathway may represent a putative therapeutic target for smoking and to mitigate the effects of smoking on depression." (PMID 36057695, 2022). "In addition, high estrogen release during PCOS increases interleukin 4 (IL-4), IL-1, IL-6, and interferon γ (IFN-γ) production and these increases are associated with depression-like symptoms in human and animal studies." (PMID 36117653, 2022). "The upper diagonal was based on men (N=370); the lower diagonal was based on women (N=259); PSS The Perceived Stress Scale; CES-D The Center for Epidemiologic Studies Depression Scale; IADLs Instrumental Activities of Daily Living; IL-6 Interleukin-6; hsCRP High sensitivity C-reactive protein." (PMID 35279110, 2022). "No covariates were significantly associated with depression variables in these models, although IL-6 approached significance (ß = 0.235, p = 0.052)." (PMID 35651828, 2022). "Additionally, it has been shown that SSRI used to treat depression reduce levels of pro-inflammatory cytokines, including interleukin-1α (IL-1α), interleukin-6 (IL-6), interleukin-8 (IL-8), interleukin-12 (IL-12), and IFN-γ." (PMID 36203121, 2022). "Additionally, elevated IL-6 levels in serum are strongly correlated with depression and anxiety symptoms." (PMID 36034871, 2022). "Similarly, our previous review has demonstrated that depression and anxiety are associated with elevated TNF-α, IL-6, IFN-α, and C-Reactive Protein (CRP) levels." (PMID 35053845, 2022). "As secondary aims, we explored if IL-6 levels may be related to self-reported psychopathological dimensions of depression (i.e. symptoms severity and cognitive biases) and seed based rs-FC of brain regions structurally associated with the cytokine." (PMID 36187407, 2022). "Thus, pro-inflammatory mediators, such as interleukin (IL)-6, IL-17, and tumor necrosis factor (TNF)-α, have been associated with depression in SpA." (PMID 36294416, 2022). "Furthermore, the proinflammatory cytokines TNF-α, IL-1β, and IL-6 have been reported to be raised in rodents that exhibited a depression-like phenotype." (PMID 35939172, 2022). "In addition, the POWER study demonstrated a strong correlation between patients with major depressive disorder and the IL-6 and TNF-α sweat levels." (PMID 36556392, 2022). "The link between inflammation with increased concentrations of C-reactive protein, ferritin, and interleukin-6; with depression might also explain some of the psychiatric morbidity." (PMID 36040960, 2022).
depression (continued). "As secondary aims, we explored if IL-6 levels may be related to self-reported psychopathological dimensions of depression (i.e. symptoms severity and cognitive biases) and rs-FC of brain regions structurally associated with the cytokine." (PMID 36187407, 2022). "In the setting of human depression, correlations between adipose tissue mass and inflammation have been much less studied, assessment of inflammatory markers was limited to measures of IL-6 and TNF–α and findings to date are somewhat contradictory." (PMID 35444568, 2022). "For example, IL-6 concentrations have been shown to be increased in patients with depression." (PMID 36045388, 2022). "Similarly, a previous systematic review and meta-analysis showed that the expression levels of IL-1β and IL-6 were significantly elevated in elderly patients with depression." (PMID 35496273, 2022). "Age is positively associated with depression and IL-6, which indicates that older TBI patients are more likely to develop post-injury depression and IL-6 may have a greater impact in older populations." (PMID 35815027, 2022). "In another study, the administration of Faecalibacterium prausnitzii via oral gavage for 4 weeks in a chronic unpredictable mild stress model in rats resulted in decreased depression-like behaviors accompanied by increased IL-10 and decreased IL-6 and CRP levels." (PMID 35546876, 2022). "The results of this study showed that the level of serum IL-6 and IL-17 in patients with depression before treatment was positively correlated with the amount of negative life event stimulation experienced, but not with the amount of positive life event stimulation experienced." (PMID 35615531, 2022). "Furthermore, clinical researches showed that patients with depression had elevated IL-1β, IL-6, and TNF-α levels." (PMID 36578534, 2022). "In addition, AC-induced behavioural changes correlate with increased serum IL-6 levels and brain IL-1β mRNA, with these data being analogous to those reported previously in animal models of depression-like behaviour and in MDD." (PMID 34888704, 2022). "High levels of peripheral IL-6, a pro-inflammatory cytokine, have been indicated as a key element of the bipolar disorder (BD), allowing to differentiate BD from major depression with high accuracy and to early detect poor responders to antidepressant treatments." (PMID 36187407, 2022). "Peripheral IL-6 plays an important role in depression-like phenotype after social defeat stress." (PMID 36034871, 2022). "Some studies have suggested a role for IL-6 in development of depression." (PMID 36368945, 2022). "Furthermore, childhood sexual, emotional, and physical abuse interact with depression to predict higher concentrations of IL-6 in the second trimester in Latina adolescents." (PMID 35836664, 2022). "Furthermore, a large body of evidence has shown that major depression is characterized by disrupted inflammatory pathways, including cytokine expression, such as interleukin-1b (IL-1b), IL-6, interferon g (IFN-g) and tumor necrosis factor-a (TNF-a) or IL-17." (PMID 35407663, 2022). "Some scholars supported the idea that the symptoms and subtypes of depression influence IL-6 levels and suggested that using other depression-related cytokines or their receptors as biomarkers may help to classify MDD biological subtypes." (PMID 36405925, 2022). "While studies generally agree that cytokines such as IL-6 and TNF-α are correlated with depression, the role of CRP (a cytokine that generally exhibits robust correlations with depression) specifically in HIV-associated depression is a major area of debate." (PMID 35618889, 2022). "Moreover, Lacticaseibacillus paracasei NK112 exerted protective effects against Escherichia coli-induced depression through decreasing the expression of IL-1α, IL-6, and TNF-α, and inhibiting the activity of NF-κB in the hippocampus." (PMID 36358502, 2022).
depression (continued). "In addition, peripheral increased cytokines such as tumor necrosis factor (TNF)-α and interleukin (IL)-6 have been reported in individuals with the comorbidity of depression and pain." (PMID 35370832, 2022). "Kaempferol and quercetin had been reported to relieve symptoms of depression and exhibited antidepression effects through acting on interleukin-6 (IL6), mitogen-activated protein kinase 1 (MAPK1), signal transducer, and activator of transcription 3 (STAT3) and transcription factor AP-1 (JUN)." (PMID 36045654, 2022). "The levels of TNF-α and IL-6 were positively correlated with the severity of depression." (PMID 36431060, 2022). "Based on the evidence in younger patients with depression, we hypothesized that depressed geriatric patients had elevated levels of IL-6, IL-8 and TNF-α compared to controls." (PMID 36172507, 2022). "However, anti-IL6 DMARDs do show an improvement in pain and fatigue with lower levels of depression." (PMID 36422176, 2022). "Further genetic and immunological investigation is necessary to determine whether CRP, IL-6, NFL, or other inflammatory cytokines may have a causal relationship with depression." (PMID 35618889, 2022). "The current study found that the serum IL-6 level was positively associated with depression; however, this association was not significant after controlling for the age effect." (PMID 35815027, 2022). "This fits our hypothesis that increased IL-17A and IL-6/TGF-β might contribute to depression-like behaviors." (PMID 36430328, 2022). "Moreover, the cytokines that appeared increased in plasma after ISO, TNFα, IL6, and IL1β, are also the ones shared between depression and heart failure." (PMID 35936761, 2022). "IL-6 is the most commonly raised immune cytokine in depression." (PMID 35977923, 2022). "In addition, exercise training can block the proinflammatory factors IL-2 and IL-6, accelerate the transformation of microglia into M2, regulate gut flora, and lower the incidence of depression following stroke." (PMID 36389714, 2022). "On the other hand, it has been suggested that increasing of pro-inflammatory cytokines including IL-1β, IL-6 and hs-CRP elevates function of mitochondria and reactive oxygen species (ROS) that by affecting function of neurons could cause depression." (PMID 36368945, 2022). "In a study of mental health disorders in children and adolescents, there was a positive association between depression and IL-6, unlike the negative association we found here." (PMID 36158450, 2022). "Elevated IL-1β, IL-6 and lowered IL-10 in the model rats indicated there may be a low Th2 or/and M2 immune response in pain and depression comorbidities." (PMID 35733107, 2022). "Inflammation is not the only physiological state in which cytokines such as CRP and IL-6 serve a function, which complicates any inferences we may make about their role in HIV-associated depression." (PMID 35618889, 2022). "Greater levels of pro-inflammatory cytokines, such as TNFα and IL-6, have been found in patients suffering from depression, and this is potentially due to structural and functional changes being caused in the central nervous system, particularly the hippocampus." (PMID 35277015, 2022). "Earlier studies also confirmed a strong relationship between depression and an increase in Il-6 and TNF-α, but their increase, according to researchers, was similar regardless of whether it was the first depressive episode or a subsequent one." (PMID 35407663, 2022). "Moreover, a higher baseline IL-6 level, as well as its reduction, were significantly correlated with a decrease in unipolar depression severity following 12 weeks of physical exercise." (PMID 36291336, 2022). "Patients with major depression have higher levels of IL-6 than healthy controls." (PMID 36052143, 2022).